IL13 (interleukin 13)
Diseases named in the same sentence as IL13 in open-access papers (continued):
Sharing a sentence is not in itself a finding about the gene and the disease.
asthma (continued). "EV-associated ezrin released by AECs contributed to IL-13-induced epithelial damage via the TNF-α-dependent pathway and was proposed as a biomarker of asthma control." (PMID 36466836, 2022). "IL-4, IL-5, and IL-13 in BALF were measured to be about 10 times greater following the induction of asthma by OVA as compared to normal mice." (PMID 36115955, 2022). "The cytokines secreted by Th2 cells are mainly IL-4, IL-5, IL-13, and IL-9 which have different roles in the pathogenesis of asthma." (PMID 36032162, 2022). "Mechanistically, CD4+ T cells and ILC2s regulate asthma by promoting the production of IL-13 amplifying type II inflammation." (PMID 35656293, 2022). "Lebrikizumab is another humanized IgG4 monoclonal antibody targeting IL-13 that has been intensively studied in moderate-to-severe asthma." (PMID 36561741, 2022). "The recent introduction of biologic treatments, such as the anti-IgE, anti-IL-5 and anti-IL-4Rα (IL-4/IL-13) monoclonal antibodies have change the management of severe asthma." (PMID 35332239, 2022). "Subsequently, the expressions of potential biomarkers were examined through qRT-PCR analysis in the T2 asthma coreinteracting cellular factor (IL-13/IL-33) induced experimental model." (PMID 35480331, 2022). "Accumulating evidence from ex vivo studies as well as AR or asthma animal models lend credence to the further assessment of IL-4/IL-13-targeted therapy in AR and asthma patients." (PMID 35663523, 2022). "Targeting the IL-4/IL-13 axis at various levels of its signaling pathway has emerged as promising targeted therapy in both AR and asthma patient populations." (PMID 35663523, 2022). "The Th2-related cytokines such as IL-4 and IL-13 are of vital importance in the pathological process of asthma by inducing IgE production and airway mucus hypersecretion." (PMID 35281601, 2022). "EWAS of childhood asthma using PMBCs from the participants in the Inner-City Asthma Consortium identified several asthma-related genes such as IL13, IL4, and RUNX3 with differentially methylated regions (DMRs)." (PMID 35055381, 2022). "If Th2-type cytokines IL-4 and IL-13 involvement in subepithelial fibrosis in asthma is acknowledged, pro-fibrotic effects of IL-17 are also well-documented." (PMID 35386663, 2022). "Since IL-13 can induce epithelial cells to secrete mucus in asthma, the airway mucus secretion in each group of mice was also observed." (PMID 35281601, 2022). "Dupilumab, a monoclonal antibody (mAb) and a dual inhibitor of IL-4 and IL-13, has been approved for the treatment of atopic dermatitis and asthma." (PMID 36430483, 2022). "Antagonising the IL-4 receptor α subunit (IL-4Rα) interferes with the downstream IL-4/IL-13 signalling, which is central to the pathogenesis of asthma." (PMID 36140430, 2022). "The current therapeutic approach for Th2-high severe asthma is based on biologics targeting allergy molecules (IgE) and eosinophilic interleukins (IL-5, IL-4, IL-13, TSLP)." (PMID 35887589, 2022). "The IL-13 monoclonal antibodies (e.g., dupilumab, lebrikizumab, and tralokinumab) have been developed for not only allergic diseases (e.g., atopic dermatitis, asthma) but various other autoimmune diseases." (PMID 35140724, 2022). "RV infection induced IL-33 and Th2 cytokine responses in the airways of asthma patients, with IL-33 levels correlating with IL-5 and IL-13 levels." (PMID 36077310, 2022). "IL-4/IL-13 axis is important in the pathogenesis of AR and asthma in which the axis exerts a wide range of effects on inflammatory cells and structural changes to airway epithelial cells in AR and asthma." (PMID 35663523, 2022). "Together, these two pathways lead to differentiation of naive T cells into Th2 cells, releasing a large number of inflammatory factors (IL‐4, IL‐5 and IL‐13) and aggravating the progression of asthma." (PMID 35079347, 2022). "In asthma, airway inflammation caused by tumor necrosis factor (TNF)-α, IFN-γ, IL-4, and IL-13 dysregulate epithelial barrier activities." (PMID 35625578, 2022).
asthma (continued). "The mucus in IL-13-treated mice and in patients with asthma contains a high proportion of the mucin Muc5AC." (PMID 35997279, 2022). "As noted, asthma is also a manifestation of excessive activation of Th2 cells, which leads to increased secretion of IL-4, IL-5, and IL-13 in asthmatic mice." (PMID 35682783, 2022). "Mice exposed to A. niger develop airway hyperresponsiveness, the physiologic sine qua non of asthma, increased production of the type 2 cytokines IL-4, IL-5, and IL-13 in the lungs, along with an influx of eosinophils and elevated serum IgE levels." (PMID 35281012, 2022). "Observational studies on type-2 cytokines in sputum also showed that mean IL-4, IL-5, and IL-13 mRNA expression and concentrations of these cytokines were increased in elderly patients with asthma." (PMID 36291665, 2022). "IL13 is a type of T-help 2 type cytokine and plays a key role in the pathophysiology of asthma and COPD." (PMID 36497047, 2022). "During the inflammatory response, eosinophils also induce lymphocytes to synthesize and release cytokines such as IL-1β, IL-4, IL-6, and IL-13, which promote and exacerbate asthma attacks." (PMID 36408342, 2022). "Otherwise, asthma mice pretreated with Imuno TF presented reduced concentrations of IL-4 (5A), IL-5 (5B), and IL-13 (5C) in lung tissue compared to asthma mice." (PMID 36685604, 2022). "Pulmonary eosinophilia and high amounts of IL-4, IL-5, IL-13 and IgE in the lungs and serum are also characteristic of asthma." (PMID 36145419, 2022). "We demonstrated that, like RUNX2, HMGB1 expression was increased in bronchial epithelium of asthma patients, IL‐13‐stimulated human bronchial epithelial cells and OVA‐challenged mice airways." (PMID 35093061, 2022). "Together, these results suggest that CLCA1 mediates the regulatory effect of IL-13 on pediatric asthma." (PMID 36313877, 2022). "Discovered DMRs annotated to genes implicated in allergy and asthma, Th2 activation and eosinophilia (EPX, IL4, IL13, PRG2, CLC and ZFMP1) and genes previously associated with asthma and IgE in an EWAS of blood (ACOT7, SLC25A25)." (PMID 35344303, 2022). "Among the various factors related to asthma progression, the Th2 cytokines including IL-13, IL-5, and IL-4 play crucial roles in the advancement of the disease." (PMID 35892624, 2022). "The major flavonodial compound in the extract (vitexin) was shown to reduce the levels of inflammatory cytokines such as IL4, IL5, and IL13 by 64%, 95%, and 65% in an induced asthma model at concentration of 1 mg/kg." (PMID 35050106, 2022). "IL-4– and IL-13–driven epithelial cell expression of 15 lipoxygenase 1 (15LO1) is a consistent feature of eosinophil-dominated asthma known as type 2–high (T2-high) asthma." (PMID 34981786, 2022). "Raised IL-13 has been noted in the plasma and PMBCs of children affected by ASD, particularly those with comorbid asthma (although IL-13 is known to be skewed in those with co-morbid atopic conditions)." (PMID 35250672, 2022). "Interleukin-13 (IL-13) is a cytokine implemented in various allergic inflammations, so it can be exploited for the treatment of diseases such as asthma and atopic dermatitis." (PMID 35011562, 2022). "In this study, sputum TIPE2 levels were significantly increased in patients with EA and positively correlated with sputum IL-4, IL-5, and IL-13 that promoted eosinophilic inflammation in asthma." (PMID 35572500, 2022). "Interleukin 13 (IL-13) secreted by Th2 cells is associated with airway inflammation in asthma, and data based on transcriptome sequencing of asthmatic patients confirmed that a positive correlation exists between the DPP4 gene and IL-13 mRNA levels." (PMID 35967302, 2022). "In patients with moderate-to-severe asthma, the treatment with dupilumab, an anti-IL-4Rα antibody, efficiently reduces severe exacerbation and improves lung functions, suggesting the involvement of IL-4 and/or IL-13 in the pathogenesis of asthma." (PMID 35693800, 2022).
asthma (continued). "Specifically, IL-13 is produced by activated T cells, basophils, eosinophils, and mast cells and is thought to be a central molecular mediator of inflammation in asthma." (PMID 35330333, 2022). "Periostin-expressing dendritic cells (DCs) from HDM-challenged wild-type mice kept asthma-like features and IL-13 responses after transferring into periostin null mice." (PMID 36611844, 2022). "Asthma pathogenesis is strongly influenced by a number of mediators of inflammation, such as IgE, IL-3, IL-4, IL-5, IL-9, IL-13, IL-33 and TSLP, with many more being discovered." (PMID 36561741, 2022). "Asthma is characterized by chronic airway inflammation, in which Th2 cells promote the accumulation of eosinophils by secreting interleukin IL-4, IL-5, and IL-13 is the key pathogenesis of asthma." (PMID 35287655, 2022). "Even if the functional roles of IL-4 and IL-13 are quite overlapping, it is however plausible that these two sister cytokines exert distinct pathobiological actions in asthma." (PMID 35350765, 2022). "After cortisol hormone therapy, the levels of IL-4, IL-5, and IL-8 in the sputum of asthma patients were reduced, IL-13 expression was decreased in the bronchial epithelium in asthma patients." (PMID 35578178, 2022). "Recently, a phase I trial studying the effect of a bispecific anti-IL-13 and anti-IL-17A antibody in asthma was early terminated due to high frequency of treatment immunization." (PMID 35386663, 2022). "Since our study involves severe asthma patients with possibly a more severe type-2 inflammation and a higher amount of circulating cytokines, we tried to measure IL-13 levels directly in the serum." (PMID 36326393, 2022). "We determined the effect of miR-155 deficiency on FcεRI-induced production of the proinflammatory cytokines TNF and IL-6, and the mucus-promoting cytokine IL-13, which plays a prominent role in asthma." (PMID 36211602, 2022). "Due to its key role in eosinophil development, release and recruitment to tissues, IL-5 has been identified as alongside IL-4 and IL-13 as key cytokines behind the pathophysiology of T2 asthma." (PMID 36232470, 2022). "Asthma is traditionally thought to result from inflammation driven by T2 high responses and mediated by cytokines including IL-4, IL-5, and IL-13, which are often produced after the recognition of allergens." (PMID 35330333, 2022). "IL-4 and IL-13 have been studied for their involvement in the pathogenesis of allergic disorders such as asthma and atopic dermatitis through the activation of eosinophils and the production of immunoglobulin E (IgE) by B cells." (PMID 36235579, 2022). "T helper cells are a key regulator during asthma pathogenesis; they regulate the secretion of many cytokines, including IL-13, IL-5 and IL-4 and involved in innate type 2 immunity." (PMID 36201519, 2022). "Completed and ongoing clinical trials of therapeutic antibodies targeting IL-4/IL-13 axis and their receptors in AR and asthma patients." (PMID 35663523, 2022). "Previous data reported various cytokines, such as IL-4, IL-5, IL-13, and IL-33, increased in patients with asthma and AR in serum or lower respiratory tract specimens." (PMID 35348596, 2022). "Conversely, STAT6 is a transcription factor present in Th2 cells with ability to induce secretion of IL-4, IL-5, and IL-13, which are responsible for the main features of asthma." (PMID 36685604, 2022). "M2 macrophages, characterized by their expression of Mrc1, Arg1, and Chil3 are well-qualified candidates as they secrete IL-13, are known to activate T cells and are upregulated in the blood of asthma patients." (PMID 35697721, 2022). "Asthma is an allergic disease of immune imbalance, and overactivation of Th2 cells is induced in the lung to exacerbate the secretion of IL-4, IL-5, and IL-13 cytokines." (PMID 35682783, 2022).
asthma (continued). "In particular, the pleiotropic roles of IL-4 and IL-13 in orchestrating Th2 responses in AR and asthma patients indicate that dual IL-4/IL-13 blockade is a promising therapeutic strategy for both diseases." (PMID 35663523, 2022). "Epithelial cytokines known as alarmins resulted in the production of IL-4, IL-5, and IL-13, which play key roles in asthma pathogenesis." (PMID 36077310, 2022). "RUNX2 expression was significantly increased in bronchial epithelium of asthma patients, IL‐13‐stimulated human bronchial epithelial cells and in OVA‐challenged mice airways." (PMID 35093061, 2022). "Th9 cells and IL-9 promote accumulation and activation of T cells, ILC2s, mast cells, and eosinophils and increase levels of IL-5, IL-13, and IgE in animal asthma models." (PMID 35807067, 2022). "Further, many of the prominent underlying pathological features of CRSwNP, including high expression levels of type 2 cytokines (IL-4, IL-5, and IL-13, among others) and elevated IgE, are also key contributors to the pathology of asthma." (PMID 34536215, 2022). "In asthma, airway inflammation usually involves Th2 cells, which release IL-4, IL-5, IL-9, and IL-13, and play an important role in the development of airway remodeling." (PMID 35419163, 2022). "GLP1 agonists were found to decrease eosinophilic secretion of interleukin 4, interleukin 8, and interleukin 13 in mice with asthma." (PMID 36457601, 2022). "Further studies in mice showed that the NLRP3 inflammasome was required for asthma development and expression of the cytokines IL-13, IL-5, and IL-6 in obese mice fed an HFD." (PMID 35806353, 2022). "Similar outcomes were observed in house dust mite- or OVA-challenged asthmatic mice, implying that ILC2 plays a major role in inducing airway inflammation in asthma by enhancing the production of Th2 cytokines, such as IL-5 and IL-13." (PMID 35888038, 2022). "IL-13 is involved in immune defense and allergic inflammatory responses, including asthma, as part of the Th2 pathway, and has a role in converting 25(OH)D3 to its active metabolite 1,25(OH)2D3 in bronchial epithelial cells." (PMID 35215452, 2022). "Our results suggest that circulating ILC2s in patients with asthma are preactivated via the IL-4 receptor signaling pathway and produce IL-5 and IL-13 vigorously by stimulation." (PMID 37779537, 2022). "While this study suggests that CLCA1-mediated IL-13 has a role in the regulation of pediatric asthma, several aspects remain to be improved." (PMID 36313877, 2022). "We found that the expression of CLCA1 and IL-13 were positively correlated in pediatric asthma relative to healthy controls." (PMID 36313877, 2022). "According to the results, we can get the conclusion that Ferr-1 and 3-MA ameliorated ferroptosis in OVA-induced asthma model and in IL-13-challenged BEAS-2B cells, which provides a new strategy for the clinical treatment of asthma." (PMID 35154576, 2022). "It was demonstrated that IL-13-induced airway mucus obstruction was an important feature of type 2 high asthma, and that IL-13 generally reduced innate airway defenses, resulting in a pathological mucus secretome that prevented mucociliary motility." (PMID 36524132, 2022). "Discovered DMRs and CpGs were annotated to genes reported to be associated with allergic asthma, Th2 activation, and eosinophilia (EPX, IL4, IL13), as well as to genes ACOT7 and SLC25A25 implicated in a blood EWAS of asthma and IgE." (PMID 35055381, 2022). "Taken together, all these actions exerted on airway structural cells by IL-13 explain its central role in the development of airway remodeling in asthma." (PMID 35746582, 2022). "IL-13 is crucial to the pathogenesis of asthma; overexpression of IL-13 significantly induces the occurrence of allergic asthma in a mouse model." (PMID 35572600, 2022). "IL-13 plays a key role in T2 asthma and blocking its receptor IL-4Rα with the antibody dupilumab is effective in controlling severe T2 asthma and preventing exacerbations." (PMID 35608088, 2022).
asthma (continued). "We found that at low levels of eosinophils, the secretion of cytokines such as L-12p70, IL-13, and IL-4 in patients with asthma increased, while in the ACO group, the opposite result was shown that most cytokines had a decreasing trend." (PMID 36311545, 2022). "It is thus possible that the genetic control of IL-13 contributes to shape the individual susceptibility to asthma, which is associated with some polymorphisms identified in the RAD50-IL-13 region of chromosome 5q31.1." (PMID 35350765, 2022). "Representatively, the eosinophil, a major cell type activated by TNF-α, has a key role to mediate pulmonary inflammation and promote airway remodeling by producing IL-13, resulting in mucus hypersecretion in asthma." (PMID 35335934, 2022). "Most treatments of the type 2 (T2) target phenotype of asthma, in which IL-4, IL-5, and IL-13 modulate the central signals of inflammatory reactions." (PMID 35327702, 2022). "To determine the relationship between PRB1 and type 2‐high asthma further, we detected the levels of IL‐2, IL‐4, IL‐5, IL‐6, IL‐10, IL‐13, IL‐17, and INF‐γ in the induced sputum supernatant." (PMID 35344278, 2022). "The newest treatment options for severe uncontrolled asthma include the mAbs anti-IL-4/IL-13 dupilumab and the anti-thymic stromal lymphopoietin (TSLP) tezepelumab." (PMID 36140430, 2022). "Among them, Th2 cells play a major role in asthma pathogenesis by secreting various cytokines such as IL-4, IL-5, IL-9, and IL-13, while IFN-γ secreted by Th1 inhibits Th2 function." (PMID 35815290, 2022). "A study showed that the aberrant expression of immune-related miRNAs (miR-146a and miR-106b) and inflammatory cytokines (IL-5 and IL-13) among asthmatic children led to their probable role in asthma pathogenesis." (PMID 36459329, 2022). "A humanized monoclonal IgG4 antibody called dupilumab binds to the alpha subunit of the interleukin-4 receptor (IL-4Rα) and inhibits the signaling of IL-4 and interleukin-13 (IL-13), which has been successfully applied for atopic dermatitis and asthma." (PMID 35222408, 2022). "Combined neutralization of both IL-13 and IL-17A diminished the pathological signs of Th2/Th17 high experimental asthma in mice." (PMID 35883573, 2022). "The IL-4 level was higher in the ACO-a model than in mice with asthma and COPD, and the IL-13 level was higher in the asthma and ACO-a models than in the COPD and ACO-b models." (PMID 36474247, 2022). "Type 2 immune response driven by the type 2 cytokines, IL-4, IL-5, and IL-13, plays an important role in the pathogenesis of asthma." (PMID 35093061, 2022). "Total serum IgE and the levels of BALF Th2 cytokines/chemokines such as CCL17, CCL22, IL-13, IL-17, and periostin were elevated in the severe asthma mice compared to the saline-treated control." (PMID 35958610, 2022). "The pathogenesis of asthma is mainly mediated by type-2 inflammation, with increased production of Th2 cytokines such as IL-4, IL-5, and IL-13 by Th2 cells and ILC2s." (PMID 35625578, 2022). "Increased IL13 expression has been reported in the dysfunctional mitochondria of mice with house dust mite-induced asthma." (PMID 36497047, 2022). "p38 is able to induce the differentiation and activation of Th2 in asthma, resulting in the facilitated release of cytokines (IL-4, IL-5, and IL-13) secreted by Th2 cells." (PMID 34629023, 2021). "IL-4 and IL-13, which are produced by inflammatory cells including type 2 helper T cells during allergic inflammation including asthma, are known to induce the expression of iNOS in airway epithelial cells." (PMID 34782693, 2021). "In patients with severe asthma, IL‐13 correlated, by Spearman rank, moderately with BAL neutrophilia, 0.580, p < 0.001 but only very weakly with BAL Eosinophilia, 0.271, p = 0.017." (PMID 33411348, 2021).